BTF3 (basic transcription factor 3)
Description:
When associated with NACA, prevents inappropriate targeting of non-secretory polypeptides to the endoplasmic reticulum (ER). Binds to nascent polypeptide chains as they emerge from the ribosome and blocks their interaction with the signal recognition particle (SRP), which normally targets nascent secretory peptides to the ER. BTF3 is also a general transcription factor that can form a stable complex with RNA polymerase II. Required for the initiation of transcription.
Synonyms: NACB; BTF3a; BTF3b; BETA-NAC
Tractability: Small molecule: a structure with a bound ligand is known. PROTAC: ubiquitination databases record sites on it; its protein half-life has been measured.
Target class: Transcription factor
Gene: Protein-coding gene on chromosome 5 (73,498,408 to 73,505,667, forward strand). Ensembl gene ENSG00000145741.
Subcellular location: Cytoplasm; Nucleus
Subcellular location (Human Protein Atlas): Cytosol
Pathways (Reactome):
Disease: Dengue Virus Genome Translation and Replication
Gene Ontology:
Molecular function: protein binding; RNA binding
Biological process: negative regulation of protein localization to endoplasmic reticulum
Cellular component: cytoplasm; cytosol; nascent polypeptide-associated complex; nucleus
Genetic constraint (gnomAD): Loss-of-function variants: 12 observed, 21.01 expected, observed/expected ratio (o/e) 0.57, 90% interval 0.37 to 0.93. The upper end of that interval is the gene's LOEUF score, 0.93, which puts it in group 3 of 6, group 1 being the genes least tolerant of losing a copy. Missense variants: 212 observed, 242.69 expected, observed/expected ratio (o/e) 0.87, 90% interval 0.78 to 0.98. Synonymous variants: 96 observed, 87.21 expected, observed/expected ratio (o/e) 1.1, 90% interval 0.93 to 1.3.
Homologues: Orthologues: chimpanzee BTF3 (100% identical), dog BTF3 (99% identical), pig BTF3 (99% identical), rat Btf3 (98% identical), guinea pig BTF3 (97% identical), mouse Btf3 (79% identical), rabbit BTF3 (79% identical), Caenorhabditis elegans icd-1 (49% identical). Paralogues in human: BTF3L4 (64% identical), TAB2 (25% identical), TAB3 (21% identical).
Diseases named in the same sentence as BTF3 in open-access papers:
BTF3 is named in the same sentence as 36 diseases in open-access papers, as found by Europe PMC text mining. Sharing a sentence is not in itself a finding about the gene and the disease. The quoted sentences say what the papers report.
colorectal cancer (9 papers, 2017 to 2026). A primary or metastatic malignant neoplasm that affects the colon or rectum. "In conclusion, BTF3 is positively related to CRC and BTF3-siRNA attenuated the tumorigenicity of colorectal cancer cells via MAD2L2, MCM3 and PLK1 activity reduction." (PMID 31263147, 2019). "BTF3 protein expression levels in 90 colorectal cancer patients were evaluated using IHC which clearly indicated a significantly different expression of BTF3 detected in tissue samples from ANCT (n = 90) and CRC (n = 90)." (PMID 31263147, 2019). "Taken together, according to our microarray findings, BTF3 seems to be association with MAD2L2, MCM3, and PLK1 through regulatory effects in different stages of mitosis, which affect proliferation and cell cycle of colorectal cancer cells." (PMID 31263147, 2019). "Our investigations have revealed that BTF3 expression is upregulated in colorectal cancer tissue; BTF3 expression with 3-fold cutoff could be a good prognostic gene for CRC patients." (PMID 31263147, 2019). "The aim of our study was to elucidate the role of BTF3 in colorectal cancer (CRC) tissues." (PMID 31263147, 2019). "BTF3 also regulates proto-oncogene BMI1 to enhance epithelial-mesenchymal transition and stem cell-like traits to promote colorectal cancer development." (PMID 40651979, 2025). "It has been shown that transfection of BTF3 siRNA into HCT116 cells reduces cell viability, induces apoptosis, blocks the cell cycle, and attenuates tumorigenicity of colorectal cancer cells by decreasing the activities of MAD2L2, MCM3, and PLK147." (PMID 38203709, 2023).
prostate carcinoma (8 papers, 2013 to 2025). A carcinoma that arises from epithelial cells of the prostate gland. "In support of these findings, analyses of TCGA_prostate cancer cohorts yielded a significant association between the expression of BTF3 and RFC subunits." (PMID 33414468, 2021). "To gain insights into the molecular mechanism underlying the oncogenic role of BTF3 in prostate cancer, we performed RNA sequencing analysis to assess the effect of BTF3 silencing by siRNA on specific transcriptional changes." (PMID 33414468, 2021). "High levels of Basic Transcription Factor 3 (BTF3) have been associated with prostate cancer." (PMID 33414468, 2021). "Moreover, this recent work reveals that BTF3 expression may predict poor prognosis and act as a risk stratification marker of prostate cancer patients." (PMID 33414468, 2021). "For example, BTF3 acts as an oncogenic transcription factor through transcriptional upregulation of Replication Factor C to promote prostate cancer." (PMID 40651979, 2025). "BTF3 has been shown to regulate the proliferation, migration, and invasion of prostate cancer and DNA damage repair." (PMID 39707202, 2024). "BTF3 was largely present in epithelial cancer cells and the abundance of BTF3 protein was significantly elevated in prostate cancer tissues relative to the matched para-tumor tissues." (PMID 33414468, 2021). "We next conducted luciferase reporter assays to assess the transcriptional capability of BTF3 on RFC genes in prostate cancer cells." (PMID 33414468, 2021). "More recently, BTF3 has been shown to sustain prostate cancer stemness via interaction and stabilization of BMI129." (PMID 33414468, 2021). "Analysis of publicly available clinical data revealed significantly increased BTF3 mRNA expression in prostate cancer compared to normal control (TCGA prostate cancer)." (PMID 33414468, 2021). "BTF3 has been recently found to sustain cancer stem-like traits of prostate cancer via stabilization of BMI129." (PMID 33414468, 2021). "Subsequent quantitative reverse transcription PCR (qRT-PCR) analysis verified that silencing of BTF3 resulted in decreased expression of individual RFC genes in prostate cancer (PC-3 and DU145) and 293 T cells." (PMID 33414468, 2021). "Collectively, these results support the notion that BTF3 acts as an oncogenic transcription factor to directly upregulate the expression of RFC genes in prostate cancer cells." (PMID 33414468, 2021). "Taken together, these results suggest an important role of BTF3 in the regulation of DNA replication and DNA damage repair in prostate cancer cells." (PMID 33414468, 2021). "In the current study, we investigated the biological role of BTF3 as an oncogenic transcription factor and its potential as a predictive biomarker for the sensitivity of chemotherapy in prostate cancer." (PMID 33414468, 2021). "In the current study, we first showed that knockdown of BTF3 significantly attenuated the growth, migration and invasion of prostate cancer cells, validating the oncogenic effects of BTF3 in prostate cancer." (PMID 33414468, 2021). "We then employed a quantitative immunofluorescence approach to stratify prostate cancer using co-localization coefficients of BTF3, HINT1 and NDRG1." (PMID 24386364, 2013). "As our data indicated that BTF3 was involved in regulation of DNA replication and DNA damage repair in prostate cancer cells, we next examined the correlation of BTF3 expression with treatment response to cisplatin, a DNA crosslinking agent that causes DNA damage." (PMID 33414468, 2021). "Our findings that BTF3 promotes tumorigenesis through transcriptional upregulation of Replication Factor C (RFC) subunits thus add a new perspective on the potential oncogenic roles of BTF3 in prostate cancer." (PMID 33414468, 2021).
prostate carcinoma (continued). "Importantly, we show that enforced BTF3 overexpression in prostate cancer cells induces substantial accumulation of cisplatin-DNA adducts and render the cells more sensitive to cisplatin treatment both in vitro and in vivo." (PMID 33414468, 2021). "Collectively, BTF3-mediated transcriptional regulation of RFC subunits may account for the oncogenic action of BTF3 in prostate cancer." (PMID 33414468, 2021). "Herein, we report that BTF3 confers oncogenic activity in prostate cancer cells." (PMID 33414468, 2021). "Fixed threshold (criteria >) values for putative biomarkers for diagnosis range between 0.68 and 0.74, indicating high sensitivity for NDRG1, BTF3 and HINT1, as diagnostic markers for identifying prostate cancer in tissue cores by unbiased, quantitative immunohistochemistry." (PMID 24386364, 2013). "Additionally, BTF3 acts in prostate cancer by inhibiting the degradation of BMI1." (PMID 39707202, 2024). "Interestingly, our data suggest that BTF3 overexpression sensitizes prostate cancer cells to the DNA damaging agent cisplatin and may serve as a potential predictive marker for the selection of patient for platinum-based treatment." (PMID 33414468, 2021). "If this scenario also holds true in prostate cancer, our study may warrant further investigation of whether BTF3 silencing-induced DNA replication vulnerability sensitizes cells to PARG inhibition, a potential new treatment strategy that can be extended to treat prostate cancer patients." (PMID 33414468, 2021). "Indeed, silencing of BTF3 via shRNA resulted in significantly attenuated growth of PC-3 and DU145 prostate cancer cells cultured in both 2D and 3D conditions, enhanced apoptotic cell death, as well as mitigated migration and invasion potential." (PMID 33414468, 2021). "In our study, while BTF3 is involved in the regulation of DNA replication and repair processes, silencing of BTF3 did not render prostate cancer cells more responsive to cisplatin." (PMID 33414468, 2021). "We found that BTF3b-overexpressing tumors grew significantly faster than the control tumors, consistent with the notion that BTF3 confers gain-of-function activity in prostate cancer." (PMID 33414468, 2021). "shRNA-mediated stable knockdown of BTF3 in PC-3 and DU145 cells resulted in significantly reduced percentage of BrdU positive cells, a marker of replicative DNA synthesis in S-phase, consistent with a role for BTF3 in DNA replication in prostate cancer cells." (PMID 33414468, 2021). "BTF3, HINT1, NDRG1 and ODC1 could be developed as epithelial specific biomarkers for tissue based diagnosis and stratification of prostate cancer." (PMID 24386364, 2013). "We chose four genes BTF3, NDRG1, HINT1 and ODC1 that are up-regulated in prostate carcinoma (oncomine.org; selection criteria: p=0.0001, 2 fold change and in top 10% of genes over-expressed in the overall dataset) in at least four normal vs cancer prostate gene expression analysis datasets." (PMID 24386364, 2013). "We used quantitative immunohistochemistry to show that the expression of BTF3, HINT1, NDRG1 and ODC1 proteins is increased in prostate cancer tissue and could serve as putative targets for the investigation of carcinogenesis or biomarkers for disease." (PMID 24386364, 2013). "In addition, in vitro study revealed that overexpression of basic transcription factor 3 (BTF3) could up-regulate BMI1 expression, which is a crucial mechanism for the acquisition of a stem cells-like phenotype in prostate cancer." (PMID 36969009, 2023). "We found that the anti-BTF3 antibody, but not the isotype IgG, efficiently retrieved the proximal region of each specific RFC promoter in both 293 T and prostate cancer cells (PC-3 and DU145)." (PMID 33414468, 2021). "Furthermore, BTF3, NDRG1 and HINT1, in quantitative co-localization studies appear capable of discriminating between biochemical relapse and non-relapse prostate cancer." (PMID 24386364, 2013).
breast cancer (6 papers, 2013 to 2024). A primary or metastatic malignant neoplasm involving the breast. "The expression of BTF3 protein was dropped as the action time increased, and the growth rate of canine mammary tumor cells was slowed." (PMID 38203709, 2023). "This indicates that BTF3 is a specific binding protein for matrine in canine mammary tumor cell lines." (PMID 38203709, 2023). "As a transcription factor, BTF3 is believed to regulate gene expression by binding target promoters, and this mechanism has been reported in breast cancer." (PMID 33644029, 2020). "Inhibition of BTF3 reduces the proliferative and metastatic capacity, and sensitizes luminal breast cancer cells to PI3Kα inhibitors." (PMID 31138311, 2019). "BTF3 promotes the proliferation, survival, and migration of ER + breast cancer cells by modulating ESR1 expression and ERα-dependent transcription." (PMID 31138311, 2019). "aCT1 bound to BTF3 in our proteomic analysis and consistent with this, the gene that encodes N-cadherin, CDH2, was significantly reduced in aCT1-treated samples in our gene expression analysis using the NanoString nCounter Breast Cancer 360 panel." (PMID 38275864, 2024). "There has been no reported link between matrine and BTF3, so we investigated the changes in BTF3 after matrine action on canine mammary tumor cells from the perspective of genes and proteins." (PMID 38203709, 2023).
gastric cancer (6 papers, 2017 to 2024). A primary or metastatic malignant neoplasm involving the stomach. "In gastric cancer, BTF3 expression is associated with enhanced cell proliferation, reduced cell cycle regulation, and apoptosis and its silencing inhibits proliferation of gastric cancer cells." (PMID 28275354, 2017). "Among them, BTF3 promotes the proliferation of hepatocellular carcinoma and gastric cancer cells by up-regulating FOXM1." (PMID 39707202, 2024). "In others reports, BTF3 as one of the important transcription factors was proved in gastric cancer development and in progression by enhance transcription." (PMID 37372325, 2023). "BTF3 has also been shown to be involved in the stimulation of proliferation of cells, reducing of cell cycle regulation and gastric cancer cell apoptosis." (PMID 31263147, 2019). "We previously reported that BTF3 is involved in the development/progression of gastric cancer." (PMID 31263147, 2019).
pancreatic cancer (5 papers, 2012 to 2023). "Transcription factors, such as BTF3, are shown to control tumor-associated genes in pancreatic cancers." (PMID 34830970, 2021). "Furthermore, the gene expression of IRAG1 was upregulated in the context of pancreatic ductal adenocarcinoma (PDAC) after silencing the transcription factor basic transcription factor 3 (BTF3) in pancreatic cancer cell lines." (PMID 37372987, 2023).
colon cancer (4 papers, 2019 to 2025). "Knockdown of BTF3 suppresses cell proliferation, whereas its overexpression enhances cell migration, emphasizing its role in promoting protumorigenic phenotypes in colon cancer cells." (PMID 40754247, 2025). "In colon cancer, downregulation of BTF3 resulted in the inhibition of cell proliferation with cells in the early apoptotic phase." (PMID 34830970, 2021). "Recent reports have shown that downregulation of BTF3 attenuates tumorigenesis in colon cancer cells." (PMID 32517689, 2020). "Since cell cycle regulation is widely accepted to occur during cancer development, it is highly probable that this signaling process has a vital function in BTF3-mediated development of colon cancer." (PMID 31263147, 2019). "BTF3 is another factor contributing to colon cancer progression." (PMID 40754247, 2025).
Burkitt lymphoma (3 papers, 2012 to 2019). A rare form of malignant mature B-cell non-Hodgkin lymphoma. "For example, altered BTF3 has been linked to the apoptosis of BL60 Burkitt’s lymphoma cells." (PMID 31263147, 2019). "Furthermore, the inhibition of BTF3 participated in the repression of transcription and protein synthesis in apoptotic K562 cells, while change in BTF3 expression is linked with apoptosis in BL60 Burkitt lymphoma cells." (PMID 24971328, 2014). "For example, altered BTF3 was found to be associated with apoptosis in BL60 Burkitt lymphoma cells." (PMID 23029305, 2012).
melanoma (2 papers, 2025). A malignant, usually aggressive tumor composed of atypical, neoplastic melanocytes. "LINC00622 physically associates with BTF3 and binds to the RRAGD locus to transcriptionally enhance RRAGD expressions and further activate mTORC1 to inhibit autophagic cell death, which contributes to melanoma progression." (PMID 40651979, 2025).
ovarian carcinoma (2 papers, 2018 to 2020). A malignant neoplasm originating from the surface ovarian epithelium. "A previous study indicated that BTF3 was downregulated by miR-802 in ovarian cancer." (PMID 33644029, 2020). "Among all these RBP genes, only four showed deletion in more than 5% of TCGA ovarian cancer samples, including transcription factor BTF3, sorbin and SH3 domain-containing protein 2 (SORBS2), cold-inducible RNA-binding protein (CIRBP), and RNA-binding protein MEX3D (MEX3D)." (PMID 29548303, 2018).
pancreatic ductal adenocarcinoma (2 papers, 2013 to 2023). An infiltrating adenocarcinoma that arises from the epithelial cells of the pancreas. "BTF3 is a 27kDa protein that forms a stable complex with RNA polymerase IIB and is required for transcriptional initiation and known to be over-expressed in cells from pancreatic ductal carcinoma both in vitro and in situ." (PMID 24386364, 2013).
Cerebral ischemia (1 paper, 2021). Restriction of arterial blood supply to the brain associated with insufficient oxygenation to support the metabolic requirements of the tissue. "Then, the CK2/BTF3 complex promotes Wnt/β-catenin signal activation and subsequent transcription of the mitochondrial fusion-related gene Mfn2, resulting in remarkable neuroprotection against cerebral ischemia." (PMID 33602894, 2021).
cutaneous melanoma (1 paper, 2025). A primary melanoma arising from atypical melanocytes in the skin. "Our findings demonstrate that upregulated LINC00622 acts as a key regulator to transcriptionally enhance RRAGD expression and represses mTORC1-regulated autophagy by associating with BTF3 in cutaneous melanoma." (PMID 40651979, 2025). "Mechanistically, LINC00622 associates with and recruits BTF3 to transcriptionally enhance RRAGD expression for activating mTORC1 and thus inhibiting autophagic cell death, which contributes to the development of cutaneous melanoma." (PMID 40651979, 2025).
dental caries (1 paper, 2017). The decay of a tooth, in which it becomes softened, discolored, and/or porous. "Our data confirm the association between dental caries and genetic variation in BTF3 and AQP5 we have previously reported." (PMID 28275354, 2017).